TOX (thymocyte selection associated high mobility group box)
Description:
Transcriptional regulator with a major role in neural stem cell commitment and corticogenesis as well as in lymphoid cell development and lymphoid tissue organogenesis (By similarity). Binds to GC-rich DNA sequences in the proximity of transcription start sites and may alter chromatin structure, modifying access of transcription factors to DNA. During cortical development, controls the neural stem cell pool by inhibiting the switch from proliferative to differentiating progenitors. Beyond progenitor cells, promotes neurite outgrowth in newborn neurons migrating to reach the cortical plate. May activate or repress critical genes for neural stem cell fate such as SOX2, EOMES and ROBO2 (By similarity). Plays an essential role in the development of lymphoid tissue-inducer (LTi) cells, a subset necessary for the formation of secondary lymphoid organs: peripheral lymph nodes and Peyer's patches. Acts as a developmental checkpoint and regulates thymocyte positive selection toward T cell lineage commitment. Required for the development of various T cell subsets, including CD4-positive helper T cells, CD8-positive cytotoxic T cells, regulatory T cells and CD1D-dependent natural killer T (NKT) cells. Required for the differentiation of common lymphoid progenitors (CMP) to innate lymphoid cells (ILC) (By similarity). May regulate the NOTCH-mediated gene program, promoting differentiation of the ILC lineage. Required at the progenitor phase of NK cell development in the bone marrow to specify NK cell lineage commitment (By similarity). Upon chronic antigen stimulation, diverts T cell development by promoting the generation of exhaustive T cells, while suppressing effector and memory T cell programming. May regulate the expression of genes encoding inhibitory receptors such as PDCD1 and induce the exhaustion program, to prevent the overstimulation of T cells and activation-induced cell death (By similarity).
Synonyms: KIAA0808; TOX1
Tractability: PROTAC: ubiquitination databases record sites on it.
Gene: Protein-coding gene on chromosome 8 (58,805,412 to 59,119,279, reverse strand). Ensembl gene ENSG00000198846.
Subcellular location: Nucleus
Subcellular location (Human Protein Atlas): Nucleoli fibrillar center; Nucleoplasm
Gene Ontology:
Molecular function: protein binding; chromatin DNA binding
Biological process: natural killer cell differentiation; CD4-positive, alpha-beta T cell lineage commitment; CD4-positive, CD25-positive, alpha-beta regulatory T cell lineage commitment; CD8-positive, alpha-beta T cell lineage commitment; cerebral cortex neuron differentiation; leukocyte differentiation; NK T cell lineage commitment; positive regulation of neural precursor cell proliferation; positive regulation of neuron projection development; positive regulation of transcription by RNA polymerase II; regulation of positive thymic T cell selection; regulation of transcription by RNA polymerase II
Cellular component: nucleus
Genetic constraint (gnomAD): Loss-of-function variants: 10 observed, 52.09 expected, observed/expected ratio (o/e) 0.19, 90% interval 0.12 to 0.33. The upper end of that interval is the gene's LOEUF score, 0.33, which puts it in group 1 of 6, group 1 being the genes least tolerant of losing a copy. Missense variants: 558 observed, 685.41 expected, observed/expected ratio (o/e) 0.81, 90% interval 0.76 to 0.87. Synonymous variants: 223 observed, 253.65 expected, observed/expected ratio (o/e) 0.88, 90% interval 0.79 to 0.98.
Homologues: Orthologues: chimpanzee TOX (100% identical), macaque TOX (99% identical), dog TOX (97% identical), rabbit TOX (97% identical), guinea pig TOX (96% identical), mouse Tox (94% identical), pig TOX (94% identical), rat Tox (90% identical), tropical clawed frog tox (84% identical), zebrafish tox (64% identical), Caenorhabditis elegans hmg-4 (9% identical), Caenorhabditis elegans hmg-3 (9% identical). Paralogues in human: TOX3 (47% identical), TOX2 (44% identical), TOX4 (35% identical), HMGXB4 (16% identical), SMARCE1 (13% identical), SP100 (13% identical), UBTF (13% identical), SSRP1 (11% identical), SP140 (10% identical), HMGB1 (10% identical), HMGB2 (10% identical), HMG20B (10% identical), and 8 more.
Diseases named in the same sentence as TOX in open-access papers:
TOX is named in the same sentence as 117 diseases in open-access papers, as found by Europe PMC text mining. Sharing a sentence is not in itself a finding about the gene and the disease. The quoted sentences say what the papers report.
melanoma (14 papers, 2020 to 2026). A malignant, usually aggressive tumor composed of atypical, neoplastic melanocytes. "The low TOX expression level in the T cells was associated with enhanced overall survival rate (P = 0.0022, log-rank test) for TCGA melanoma cohort (SKCM, skin cutaneous melanoma)." (PMID 32111241, 2020). "The mRNA findings were backed up by the progressive elevation of TOX protein as exhaustion proceeded in TILs infiltrating mouse B16 melanomas or tamoxifen-inducible liver cancers, and by the expression of TOX protein in CD8+ TILs from human tumors." (PMID 40746547, 2025). "Two studies showed that haploinsufficiency of TOX improves in vivo anti-tumour efficacy of CD8+ T cells in murine models of melanoma and hepatocellular carcinoma." (PMID 39399500, 2024). "In patients with melanoma and non-small cell lung cancer, TOX expression is significantly higher in CD8+T lymphocytes, a phenomenon that is positively correlated with the expression of PD-1, TIM3, CTLA4, and other IRs." (PMID 36969216, 2023). "Although they displayed non-exhausted phenotype (low expression of inhibitory receptors), TOX-knockout T cells remained dysfunctional and showed increased apoptosis in mouse melanoma." (PMID 37398660, 2023). "The analysis of single-cell transcriptome data from patients with melanoma revealed a strong positive correlation between TOX expression level in all T cells and in CD8+ T cells." (PMID 32111241, 2020). "The authors showed that there were progressively increasing and persistent expression of TOX in Tc liver cancer and murine melanoma during tumor progression, in contrast to temporary upregulation of TOX in memory and effector cells in acute infection." (PMID 32823814, 2020). "In this study, the single-cell transcriptome profiles of melanoma patients indicated that TOX exhibited a highly specific expression pattern in the T cells." (PMID 32111241, 2020). "We found that TOX levels positively correlate with those of IC molecules in human melanoma and NSCLC." (PMID 32111241, 2020). "In our melanoma cohort, scRNA-seq analysis showed the presence of a Vδ1 subpopulation displaying an exhaustion transcriptional signature characterized primarily by high levels of transcripts for ICRs, KIRs and TOX." (PMID 41310392, 2026). "Indeed, conventional analysis of transcripts in TILs from human melanoma and non-small cell lung cancer revealed TOX as a critical driver of intratumoral T cell exhaustion which was confirmed by flow cytometry and siRNA knock-out experiments." (PMID 39399500, 2024). "Moreover, melanoma secretome induces expression of a set of transcripts encoding for protein with tumor-promoting functions including CLEC17A, FR2, SMOX, TOX and ENPP1." (PMID 38239354, 2023). "We also observe that TOX level in the TI T cells inversely correlates with overall survival and anti-PD-1 response in human melanoma and NSCLC, which suggest that TOX expression in the TI T cells can be used for patient stratification before anti-tumor immunotherapy, such as anti-PD-1 treatment." (PMID 32111241, 2020). "Finally, the TOX level in the TI T cells was found to be highly predictive of overall survival and anti-PD-1 efficacy in melanoma and NSCLC." (PMID 32111241, 2020). "Notably, TOX was the only candidate TF identified in both melanoma and NSCLC samples." (PMID 32111241, 2020). "Finally, the expression levels of TOX in the TI T cells could predict the overall survival and response to anti-PD-1 therapy in human melanoma and NSCLC." (PMID 32111241, 2020). "Interestingly, the TOX expression level in the TI T cells was inversely correlated with the anti-PD-1 immunotherapy response in two published cohorts of patients with cancer, i.e., melanoma cohorts and NSCLC cohorts." (PMID 32111241, 2020). "In melanoma, all γδ T cell subsets downregulated AP-1 transcription factors, but Vδ1 cells specifically expressed high levels of ICR, TOX and inhibitory killer Ig-like receptor (KIR) transcripts, reminiscent of exhaustion." (PMID 41310392, 2026).
melanoma (continued). "TOX exhausts CD8+T lymphocytes in mouse models (infection or tumor models) or human cancers, including melanoma, non-small cell lung carcinoma, colorectal cancer, liver cancer, bladder cancer, oral squamous cell carcinoma, acute myeloid leukemia, multiple myeloma, and non-Hodgkin’s lymphoma." (PMID 36969216, 2023). "TOX, a transcription factor that drives CD8 T cells toward an exhausted state, is upregulated in SCC and melanoma TILs when compared to pCD8s, indicating that targeting TOX along with PD-1 could offset T cell exhaustion." (PMID 38023136, 2023). "In melanoma, Vδ1 cells from patients but not healthy individuals displayed a transcriptional signature reminiscent of exhaustion characterized by genes coding ICRs and TOX, while all patient-derived γδ T cells had a marked downregulation of genes coding AP-1 transcription factors." (PMID 41310392, 2026).
breast carcinoma (12 papers, 2008 to 2025). "We also analyzed the associations between the expression of TOX and adjuvant therapy after surgery in breast cancer patients." (PMID 39758401, 2025). "We aim to analyze the expression of TOX in breast cancer patients, and the association between TOX and prognostic significance in patients with breast cancer." (PMID 39758401, 2025). "Recently, novel findings showed that higher TOX expression is associated with better prognosis in breast cancer." (PMID 33743809, 2021). "The expression of TOX in surgical specimens of breast cancer were detected by immunohistochemistry staining." (PMID 39758401, 2025). "Further studies are required to elucidate the prospective mechanism by which TOX affects the function of tumor cell in breast cancer microenvironment." (PMID 39758401, 2025). "In this research, we comprehensively investigated the relationship between the expression level of TOX and clinical characteristics in breast cancer patients." (PMID 39758401, 2025). "In the current work, we examined the expression of TOX in breast cancer specimens resected from 313 cases by immunohistochemistry." (PMID 39758401, 2025). "The results indicated that the average expression of TOX in breast cancer tissues was significantly higher than that in normal adjacent tissues." (PMID 39758401, 2025). "The expression of TOX is a potential prognostic factor, and can be a promising biomarker for predicting survival in breast cancer patients." (PMID 39758401, 2025). "Meta analyses of TOX expression in breast cancers reported TOX levels paradoxically correlating with increased immune cell function and favorable prognosis." (PMID 34032638, 2021). "We subsequently analyzed the relationships between TOX expression and prognosis in four large cancer datasets (breast cancer, lung cancer, ovarian cancer, and gastric cancer) provided by Kaplan‐Meier Plotter." (PMID 32700817, 2020). "Methylation of TOX was almost exclusively seen in breast cancer, whereas TOX3 methylation was more prevalent in lung than breast cancer." (PMID 22496870, 2012). "In agreement with our findings, a recent study after evaluation of leukemia and various solid tumors including prostate, colorectal, breast, and liver cancers, also identified TOX methylation as important biomarker specifically for breast cancer." (PMID 22496870, 2012). "Treatment with either TSA or DAC led to partial re-expression of TOX in the methylated breast cancer cell lines." (PMID 22496870, 2012). "Our data revealed that TOX is hypermethylated in 43% of breast tumors and further studies demonstrated that expression of this gene in breast cancer cells is epigenetically silenced." (PMID 22496870, 2012). "Thus, this study discovered that TOX was a potential prognostic biomarker, and high expression of TOX predicted good prognosis of patients with breast cancer, which provided a new direction for predicting survival of breast cancer patients." (PMID 39758401, 2025). "•Discovery of varying TOX expression in breast cancer tissues offers novel insights." (PMID 39758401, 2025). "We hope that the expression level of TOX in breast cancer may provide a novel biomarker for guiding treatment strategies for breast cancer patients." (PMID 39758401, 2025). "However, there has been limited research on the relationship between TOX expression and prognosis in breast cancer." (PMID 39758401, 2025). "In conclusion, we verified the expression of TOX in 313 breast cancer patients and elucidated that TOX could predict survival and prognosis." (PMID 39758401, 2025). "The expression of TOX is negatively correlated with DNA methylation in tumor cells and may serve as a novel prognostic marker for breast cancer and lung adenocarcinoma." (PMID 36140731, 2022). "Thus, these initial results suggest that TOX is a potential prognostic factor in survival of brain glioma, brain astrocytoma, breast cancer, skin melanoma, bladder transitional cell carcinoma, and, particularly, LUAD." (PMID 32700817, 2020).
breast carcinoma (continued). "Similarly, lower TOX expression is also correlated with poor prognosis in brain glioma, brain astrocytoma, breast cancer, and skin melanoma, while only bladder transitional cell carcinoma shows opposite trend." (PMID 32700817, 2020). "Finally, SLC16A12, GALR2, TOX, SPOCK2, EGFR5 and DPYS are candidate biomarkers for breast cancer (methylation range 33%–79%) with the combination of EGFR5 or TOX hypermethylation showing a sensitivity of 92% and specificity of 92%." (PMID 18446232, 2008). "Therefore, we elucidated that TOX could serve as a potential predictor for breast cancer prognosis and provide novel insights for understanding the correlation between TOX and breast cancer treatment." (PMID 39758401, 2025). "Thus, it is considered that the alteration of TOX may be a potential prognostic marker for breast cancer." (PMID 33743809, 2021). "Interestingly, this study also used the MCA/RDA assay to identify methylation of TOX, among other genes, and reported exactly similar methylation of TOX in 3/4 (75%) breast cancer cell lines (3 of the cell lines are different from those used in our study) and 10/24 (42%) in primary breast tumors." (PMID 22496870, 2012). "Our results confirmed that ASC-exos promoted the TOX, CD4, and LYZ1 expression and inhibited the Mettl7b and Serpinb2 expression in breast cancer tumors, which were significantly enriched in the Human T-cell leukemia virus 1 infection pathway." (PMID 38294569, 2024). "Conspicuously, TOX expression is significantly correlated to survival in six cancer types including LUAD, brain glioma, brain astrocytoma, breast cancer, skin melanoma, and bladder transitional cell carcinoma." (PMID 32700817, 2020). "The promoter CpG islands of TOX and TOX3 were also methylated in 20 and 25% lung, and 75 and 50% breast cancers cell lines, respectively." (PMID 22496870, 2012). "Compared to adjacent normal breast, all 6 genes except NKX2-5 showed higher methylation in breast cancer by t-test analysis (P<0.001 for DPYS and EGFR5 P = 0.01 for SLC16A12; P = 0.002 for TOX; P = 0.003 for GALR2)." (PMID 18446232, 2008). "In this regard, the differential methylation of TOX and TOX3 between lung and breast cancer, TOX2 across cigarette smoking habit, and TOX3 by the histology of lung cancer suggest, methylation of TOX subfamily genes could be important biomarkers for cancer profiling." (PMID 22496870, 2012).
acute lymphoblastic leukemia (9 papers, 2016 to 2025). Leukemia with an acute onset, characterized by the presence of lymphoblasts in the bone marrow and the peripheral blood. "Genetic alterations in TOX have been characterized in lymphocytic malignancies, including acute lymphoblastic leukemia (ALL) and lymphoma." (PMID 33743809, 2021). "Among them, the oncogenic property of TOX has been reported in T-cell acute lymphoblastic leukemia (ALL) and acute myeloid leukemia (AML)." (PMID 37032358, 2023). "TOX is highly expressed in acute lymphoblastic leukemia (ALL), particularly in T cell - ALL (T-ALL)." (PMID 34692519, 2021). "Here, we demonstrate two distinct TIM3 expression patterns (high & low) with high TOX and TOX2 levels in T-cell acute lymphoblastic leukemia (T-ALL) specimens and cell lines." (PMID 39080376, 2024). "The METTL13 loci carried TOX high mobility group box family member 4 (TOX4) and spalt-like transcription factor 2 (SALL2) genes, and the expression of those genes was changed in the human acute lymphocytic leukaemia." (PMID 39596561, 2024). "In B-cell lymphomas other than CBCL, TOX deletions, but not expression, were detected in 3/45 patients (7 %) with primary central nervous system lymphomas, and in 2/126 patients (2 %) with acute lymphoblastic leukemia, of which one had a B-precursor phenotype." (PMID 27180090, 2016). "We observed that tumor samples from T-cell acute lymphoblastic leukemia (T-ALL) patients and some T-ALL cell lines had high TOX and TOX2 expression together with a low level of TIM3 expression, contradicting previous reports that TOX and TOX2 upregulate TIM3 expression in tumor-specific T cells." (PMID 39080376, 2024).
viral infection (9 papers, 2021 to 2026). "While TOX, when co-expressed with other co-inhibitory markers, has been associated with an exhausted phenotype as a result of chronic antigen stimulation, such as in viral infections or cancer, TOX expression is also regulated by the inflammatory environment." (PMID 40502703, 2025). "Although previous studies suggest that TOX is dispensable for CD8+ T cells responding to acute viral infection, these studies were performed in young mice." (PMID 40396260, 2025). "TOX is specifically increased in dysfunctional CD8+ T cells during tumor progression or chronic viral infection and is critical for controlling the expression of coinhibitory receptors during persistent TCR stimulation." (PMID 38787791, 2024). "Indeed, TOX is highly expressed in recently or chronically stimulated but fully functional human CD8 T cells in a series of viral infections." (PMID 33507150, 2021). "To examine whether CD4 T cells become exhausted due to the lack of TCF-1 in alloimmunity, as is shown during T cell responses to viral infection, we examined the Ki-67 expression and TOX expression, in CD4 T cells from WT C57Bl/6 and TCF-1 cKO mice before and after stimulation." (PMID 36901757, 2023). "By comparing transcripts of virus-specific CD8+T lymphocytes with those of acute or chronic LCMV infection, it was found that the TOX-coding chromatin in TEX was more open and accessible during chronic viral infection, indicating epigenetic remodeling of TOX in TEX." (PMID 36969216, 2023). "Thus, TOX is a critical regulator of TCF-1hi T-cell subset persistence during CNS autoimmunity and to a lesser extent after acute resolved viral infection." (PMID 33579927, 2021). "Besides the detection of TOX in the LCMV mouse model, upregulation of TOX has also been demonstrated in human viral infectious diseases such as chronic hepatitis B (HBV), human immunodeficiency virus, HCV, Epstein-Barr virus, cytomegalovirus, and influenza (FLU)." (PMID 35734162, 2022).